KCNA5 (potassium voltage-gated channel subfamily A member 5)
Diseases named in the same sentence as KCNA5 in open-access papers:
KCNA5 is named in the same sentence as 87 diseases in open-access papers, as found by Europe PMC text mining. Sharing a sentence is not in itself a finding about the gene and the disease. The quoted sentences say what the papers report.
atrial fibrillation (34 papers, 2011 to 2026). A disorder characterized by an electrocardiographic finding of a supraventricular arrhythmia characterized by the replacement of consistent P waves by rapid oscillations or fibrillatory waves that vary in size, shape and timing and are accompanied by an irregular ventricular response. "Kv1.5 potassium channel, encoded by KCNA5, is a promising target for the treatment of atrial fibrillation, one of the common arrhythmia." (PMID 35012386, 2022). "While there is no Kv channelopathy directly associated with heritable PAH, a nonsense mutation in the KCNA5 gene has been identified in a familial case of atrial fibrillation highlighting the channels’ importance in the mammalian cardiac conduction system." (PMID 36291551, 2022). "A recent experimental study investigating patients with lone atrial fibrillation identified six novel mutations in the KCNA5 gene." (PMID 28622331, 2017). "Several KCNA5 gene mutations have been involved in atrial fibrillation, a common cardiac arrhythmia, in 1.95% of patients with absence of known predisposing factors." (PMID 24936649, 2014). "Functional mutations in the underlying KCNA5 gene have been shown to cause hereditary forms of atrial fibrillation (AF)." (PMID 28729840, 2017). "Atria-Enriched GJA5, KCNA5 and NPPA, RA-Enriched HCM4, MIR100HG, REC114 and SMAD7 and Ventricles-Enriched KCNJ2, MYH7, PHLDB2, RPL2L and SLC35F1 were associated with atrial fibrillation." (PMID 34088950, 2021). "Consistent with the key role of Kv1.5 in the human atrium, the KCNA5-LOF mutation causes atrial fibrillation." (PMID 32882918, 2020). "Similarly, atrial Pluricytes express KCNA5 at levels comparable to primary atrial cardiomyocytes and may thus be used to screen for substances that bind to or modulate the atrial-associated ion channel KV1.5 (KCNA5), a target proposed for the treatment of atrial fibrillation." (PMID 34943878, 2021).
pulmonary arterial hypertension (16 papers, 2012 to 2024). Pulmonary arterial hypertension (PAH) is a group of diseases characterized by mean pulmonary artery pressure >20 mmHg and elevated pulmonary arterial resistance leading to right heart failure. "For instance, APOLD1 and KCNA5, which are associated with pulmonary hypertension, showed similar expression patterns to BMPR2 in lung, artery and heart." (PMID 38730227, 2024). "(encoded by KCNA5) while inducing hypertrophy of pulmonary artery smooth muscle cells, thus suggesting a pathophysiological role in pulmonary arterial hypertension (PAH)." (PMID 32962281, 2020). "KCNA5 (potassium voltage-gated channel subfamily A member 5) genes, associated with pulmonary arterial hypertension (PAH), may affect the motion of the horse." (PMID 31940795, 2020). "Recently, a protective association of the KCNA5 locus with systemic sclerosis (SSc) patients with pulmonary arterial hypertension (PAH) was reported." (PMID 23270786, 2012). "Remillard and colleagues identified 17 single-nucleotide polymorphisms of the Kv1.5 gene in pulmonary arterial hypertension (PAH) patients, which may contribute to the downregulation of KCNA5, causing the increase of the vascular tone." (PMID 34959701, 2021). "Our conclusions substantiate the work of other groups, namely that patients with genetic mutations of KCNA5 exhibit pulmonary arterial hypertension and arterial fibrillation but not systemic hypertension." (PMID 27540364, 2016). "Moreover, it has been reported that primary pulmonary hypertension patients have an intrinsic reduced level of KCNA5 mRNA in their PASMCs, and this characteristic might play an important role in the pathogenesis of the disease." (PMID 23270786, 2012).
Arrhythmia (11 papers, 2014 to 2026). Any cardiac rhythm other than the normal sinus rhythm. "Moreover, human Kv1.5 (hKv1.5) is encoded by KCNA5 and KCNA5 loss-of-function mutations have been reported to produce kindred atrial arrhythmia, which suggest that the genetic alteration of hKv1.5 may substantially enhance arrhythmia susceptibility." (PMID 24663680, 2014). "In parallel, 902 arrhythmia-related genes were retrieved, yielding 24 overlapping targets, among which five hub genes (PIK3CA, CREBBP, NR3C1, SCN10A, and KCNA5) were identified." (PMID 42292832, 2026). "Moreover, calcium handling and contractile function genes (SLN, ACTC1, PLCD4, PLCZ), potential arrhythmia-related genes (MYO5B, KCNA5), and cytoskeleton and cellular organization-related genes (XIRP2, COL8A1, KCNA6) were among the most deregulated genes in rTOF ventricles." (PMID 26252659, 2015).
gastric cancer (7 papers, 2013 to 2024). A primary or metastatic malignant neoplasm involving the stomach. "Likewise, the Kv1.5 channel, encoded by the KCNA5 gene, is reported to have a low/medium expression on the surface of colorectal and stomach cancer cell lines (provided by The Human Protein Atlas)." (PMID 33267786, 2020).
glioblastoma (6 papers, 2013 to 2024). The most malignant astrocytic tumor (WHO grade IV). "It has been reported that KCNJ10, KCNA5, and KCNN4 can affect the proliferation and invasive ability of gliomas and glioblastomas by altering the cell membrane potential in excitatory cell-derived tumors." (PMID 38905316, 2024).
Hypertension (6 papers, 2013 to 2024). The presence of chronic increased pressure in the systemic arterial system. "This fact can say that KCNA5 which is known for one of causal genes of hypertension arterial was only detected by MetaQ-test and MetaQ-test improved the statistical power of QTest." (PMID 31296221, 2019). "However, the gene that has the second smallest p value in both Het-meta-Q2 (p value = 1.19e-05) and Het-meta-Q3 (p value = 2.41e-05) is KCNA5 and this gene is already known for having strong relevance to hypertension." (PMID 31296221, 2019). "‘Unknown I’ contained a diverse set of key driver genes such as SGK1, SIK1 and SLC10A6 (sodium metabolism and hypertension), MT2A and TSC22D3 (glucocorticoid signaling), GADD45G, ERRFI1, GPRC5A, and EGFR (cell growth and apoptosis), and CEBPB, CEBPD, and KCNA5 (heart development and function)." (PMID 25033284, 2014). "Finally, the potassium channels coded by KCNA5 and KCNQ1 can be blocked by quinidine, amiodarone, tedisamil and flecainide (antianginal and antiarrhythmic drugs) or opened by nicorandil (frequently used against hypertension)." (PMID 24165276, 2013).
Ewing sarcoma (4 papers, 2017 to 2025). A small round cell tumor that lacks morphologic, immunohistochemical, and electron microscopic evidence of neuroectodermal differentiation. "Separately, suppression of KCNA5 in Ewing sarcoma and neuroblastoma cell lines has been shown to contribute to the survival of these malignant cells under hypoxic conditions, which would make more intuitive sense in the context of ccRCC organoid survival." (PMID 40352330, 2025). "A recent study showed a down-regulation of KCNA5 in Ewing sarcoma that was related to the hypermethylation of the gene promoter." (PMID 33267786, 2020). "Potassium voltage-gated channel subfamily A member 5 (KCNA5) is a protein coding gene involved in tumor cell proliferation in Ewing sarcoma, while its role in CRC is still unknown." (PMID 30987631, 2019). "Speculatively, as well as Ewing sarcoma, methylation of KCNA5 could be responsible for stable silencing of this gene in CRC, thus contributing to proliferation of tumor cells." (PMID 30987631, 2019).
breast carcinoma (3 papers, 2015 to 2018). "Notably, four lncRNAs (lnc-RPRD2-3:1, lnc-KCNA5-3:4, lnc-CFP-1:1 and lnc-CD164L2-1:1) correlated strongly with the mutation status of IGF2R, a tumor suppressor commonly mutated in human liver and breast cancer." (PMID 29416609, 2018).
Obesity (3 papers, 2017 to 2025). Accumulation of substantial excess body fat. "Therefore, we focused our observations on identifying a possible relation between KCNA3 and KCNA5 expression and patients’ clinical features and tumor risk factors, such as age, sex, obesity, and smoking." (PMID 36978819, 2023).
gastric adenocarcinoma (2 papers, 2023 to 2025). "While other potassium voltage-gated genes such as KCNA2, KCNA3, and KCNA5 have been investigated across various cancers—including skin melanoma, uterine corpus endometrial carcinoma, gastric adenocarcinoma, LUAD, and LUSC in-depth studies of KCNA7’s expression in cancer remain lacking." (PMID 40568194, 2025).
gout (2 papers, 2022 to 2025). A condition characterized by painful swelling of the joints, which is caused by deposition of urate crystals. "Compared with the normal group, the PTGS2 and TNF expression levels were dramatically higher in the gout group, and the expression of KCNA5 was prominently lower in the gout group." (PMID 40430440, 2025). "In total, three candidate targets including KCNA5, PTGS2, and TNF were identified as having genetic causality with gout and were selected for further analysis as critical targets." (PMID 40430440, 2025). "The systemic immune and inflammatory responses of the body gradually decrease during the evolution of gout from the acute phase to the remission phase, though the KCNA5 level in B cells and neutrophil cells was raised, and PTGS2 and TNF in B cells, macrophages, and monocytes were decreased." (PMID 40430440, 2025). "During the evolution from the acute phase to the remission phase of gout, KCNA5 in B cells and neutrophil cells was raised significantly, PTGS2 in B cells, macrophages, and monocytes was decreased significantly, and TNF in B cells and monocytes was also decreased significantly." (PMID 40430440, 2025). "The results of the MR analysis with good sensitivity suggested a causal relationship between candidate genes (KCNA5, PTGS2, and TNF) and gout, in which high levels of PTGS2 increase the hazard of gout, while KCNA5 and TNF can diminish the occurrence of gout." (PMID 40430440, 2025). "KCNA5, PTGS2, and TNF were identified as crucial targets for Bi-Qi capsules in the treatment of gout, which might provide new evidence for the future clinical application of Bi-Qi capsules." (PMID 40430440, 2025). "Therefore, we believe that KCNA5, PTGS2, and TNF may perform a key function in the treatment of gout with Bi-Qi capsules." (PMID 40430440, 2025). "In the LOO analysis, it was discovered that no single SNP strongly altered the holistic forest plot of KCNA5, PTGS2, and TNF for gout." (PMID 40430440, 2025).
colonic adenomas (1 paper, 2023). "ElaC ribonuclease Z 2 (ELAC2) is primarily associated with prostate cancer, and MARCH6, along with ACSM2B, DEF8, DIS3L, and KCNA5 gene variants, have not been associated with colonic adenomas yet." (PMID 36765865, 2023).
colorectal tumours (1 paper, 2020).
polycystic ovary syndrome (1 paper, 2024). A disorder that manifests as multiple cysts on the ovaries. "In addition, miR-3940-5p is a hub miRNA upregulated in granulosa cells from patients with polycystic ovary syndrome and promotes granulosa cell proliferation by targeting KCNA5." (PMID 38501059, 2024).
cancer (22 papers, 2012 to 2025). A tumor composed of atypical neoplastic, often pleomorphic cells that invade other tissues. "In Ewing’s sarcoma, the epigenetic repression of the KCNA5 gene, which encodes Kv1.5 channel, is carried out thanks to the action of the PcG proteins through DNA hypermethylation, increasing in this case cancer cell proliferation." (PMID 30011966, 2018). "To this end, we determined whether the expression of KCNA3 and KCNA5 correlated with tumor stage progression, age, sex, and some specific cancer risk factors." (PMID 36978819, 2023). "PcG-dependent inhibition of the Kv1.5 channel gene KCNA5 contributes to cancer cell survival under stressful conditions." (PMID 39744692, 2025). "Overall, these data highlighted SKCM, UCEC, STAD, LUSC, and LUAD to be the five cancers with the highest KCNAs mutation frequency and revealed KCNA2, KCNA3, and KCNA5 to be the most expressed KCNA family genes in these tumours." (PMID 36978819, 2023). "To explore the prognostic significance of KCNA2, KCNA3, and KCNA5 expression in cancer patients, we took advantage of the Kaplan–Meier analysis by sorting samples for high and low KCNAs expression according to the quartile KCNAs mRNA level." (PMID 36978819, 2023). "The second set of three genes, GNAO1, GRIA4 and KCNA5, has been less researched, with only a few studies related to cancer." (PMID 30987631, 2019). "We evaluated the overall genetic alterations in all KCNA genes (KCNA1, KCNA2, KCNA3, KCNA4, KCNA5, KCNA6, KCNA7, KCNA10) using the TCGA Pan-Cancer Atlas dataset, collecting data from 32 human cancers (10,953 patients in total)." (PMID 36978819, 2023). "Contrary to KCNA3 and KCNA5, KCNA2 has no prognostic value for any of the considered cancers." (PMID 36978819, 2023).
tumor (12 papers, 2013 to 2025). "For example, in the granulosa-like tumor cell line, miR-1388 promotes cell cycle progression by increasing cyclin D1 and decreasing p21 levels by targeting potassium voltage-gated channel subfamily A member 5 (KCNA5)." (PMID 34068244, 2021). "Specifically, potassium channels such as Kv10.2 (EAG2), Kv2.2 (KCNB2), Kv1.5 (KCNA5), and Kir2.1 (KCNJ2) were upregulated in the MB tumor tissues and primary cultures." (PMID 40150732, 2025). "However, one mutation (ERBB2) found in both plasma and stool and another mutation (KCNA5 (potassium voltage-gated channel subfamily A member 5)) observed only in stool could not be detected in the resected tumor tissue." (PMID 38766867, 2024). "As for KCNA5, the expression of the ion channel in STAD patients drastically and significantly decreases in the different tumor stages compared to healthy tissues." (PMID 36978819, 2023). "With KCNA2, KCNA3, and KCNA5 being the most abundant transcripts of the Shaker gene family in SKCM, UCEC, STAD, LUSC, and LUAD, we compared their expression levels in both tumour and normal samples." (PMID 36978819, 2023). "For KCNA5, the mean gene copy number was 0.007 (range, 0.000 to 0.042) and 0.005 (range, 0.000 to 0.020) for the GC and CRC tumour tissues, respectively." (PMID 33267786, 2020).
gastrointestinal tumours (1 paper, 2020). "Than and colleagues have shown that the expression of KCNA5 is inversely correlated with the progression of gastrointestinal tumours, which agrees with our results." (PMID 33267786, 2020).
KCNA5 also shares sentences with these, for which no sentence is quoted: pulmonary hypertension (7 papers); glioma (4); osteosarcoma (4); heart failure (3); infection (3); lymphoma (3); astrocytomas (2); brain tumor (2); cardiovascular disease (2); colorectal cancer (2); diabetes (2); epilepsy (2); gastric tumors (2); heart disease (2); myocardial infarction (2); skin cutaneous melanoma (2); systemic sclerosis (2); type 1 diabetes mellitus (2); uterine corpus endometrial carcinoma (2); Ventricular arrhythmia (2); adenoma (1); anxiety disorder (1); Ataxia (1); autoimmune disease (1); bladder tumors (1); blood cancers (1); Burkitt lymphoma (1); cardiac arrhythmia (1); channelopathies (1); Cognitive impairment (1).
A further 40 diseases each share a sentence with KCNA5 in 1 paper.